APP (amyloid beta precursor protein)
Diseases named in the same sentence as APP in open-access papers (continued):
Sharing a sentence is not in itself a finding about the gene and the disease.
amyloid (continued). "DA5‐CH has shown good effects in the APP/PS1 mouse model of AD, rescuing memory formation, synaptic plasticity, and reducing the amyloid plaque load in the brain while normalizing PI3k and Akt activity, two kinases that are activate by insulin receptor activation." (PMID 31960630, 2020). "MBNL sequestration by CUG expansion RNAs in DM1 results in enhanced APP exon 7 skipping, while HNRNPA1 knockdown leads to expression of full-length APP (+exon 7), which has been suggested to lead to increases in Aβ peptide secretion and amyloid plaques." (PMID 32086392, 2020). "This points towards Aβ/ferritin interaction as a probable source of the increased levels of mixed oxidation state Fe2+ and Fe0 phases previously observed within brain tissue from the APP/PS1 model of AD, in human AD tissue, and in isolated amyloid plaque cores." (PMID 32587293, 2020). "Importantly, these compounds similarly enhanced mitophagy and restored normal mitochondria in APP/PS1 mice, which resulted in alleviation of amyloid pathology and improved cognitive/behavioral functions." (PMID 32471464, 2020). "Recently, CN-105 was tested in a mouse model of AD (APP/PS1/APOE4TR mice) and the results showed that amyloid pathology and spatial learning deficits were reduced when the peptide treatment started in younger (14-18 weeks of age) but not older (25-28 weeks of age) mice." (PMID 32899606, 2020). "Genetic knockdown of REV‐ERBs also enhanced Aβ uptake by microglia, and global deletion of REV‐ERBα strikingly reduced amyloid plaque burden without alteration of APP processing enzymes and amyloid precursor protein (APP) in the brain of 5XFAD mice." (PMID 31800167, 2020). "Thus, it appears possible that the nature of amyloid plaques is different between the APPPS1 and APP-KI mice." (PMID 32510331, 2020). "However, others failed to observe a significant effect of chronic liraglutide treatment on cerebral Aβ plaque formation in two transgenic APP/PS1 mouse models with low and high grade of amyloidosis." (PMID 32143329, 2020). "In vivo, germline or conditional ablation of C3aR1 in APP/PS1 or 5xFAD amyloidosis mouse models has not been reported." (PMID 31924226, 2020). "Both lines, which produce humanized Aβ without overexpressing APP, show pronounced Aβ amyloidosis, gliosis, and memory deficits." (PMID 31160584, 2019). "ApoA-I could be an interesting target for a CAA-directed therapy as it was observed that APP/PS1 mice overexpressing ApoA-I or injection of ApoA-I reduced both astrogliosis and cerebral amyloid burden." (PMID 31847365, 2019). "Using APP/PS1 mice to model human AD pathophysiology, in the present study we test the hypothesis that amyloid plaque reduction and cognitive improvement mediated by geniposide are correlated to mTOR inhibition and enhanced autophagy." (PMID 30684442, 2019). "These mice develop amyloid plaque and a significant learning deficit prior to 1 year of age, attributed to excess Aβ1–42 release without APP overexpression." (PMID 31920540, 2019). "In particular, the average of both DSI and OSI was lower in APP/PSEN1 mice as compared with wild-type animals (P = 0.0002 and P = 0.0008, respectively), therefore demonstrating impaired tuning to visual stimulation in this model of amyloidosis." (PMID 30760557, 2019). "Overall Na/K-ATPase activity was decreased in the amyloid-containing hippocampi of the APP+PS1 mice, but not in the amyloid-free cerebellum, which correlates with endogenous AβOs in human frontal cortex, but not in cerebellum." (PMID 31736856, 2019). "We confirmed no alteration of the astrocytes recruitment around the amyloid plaques in APP/PS1 treated with L41." (PMID 30885273, 2019). "This is in agreement with several other recent publications that do not find ER stress in APP/PS1 double-transgenic mouse models of amyloidosis." (PMID 30315100, 2018).
amyloid (continued). "Here, we investigated detection of amyloid plaques by Gd-stained MRI in five mouse models of amyloidosis (APPSL/PS1M146L, APP/PS1dE9, APP23, APPSwDI, and 3xTg) presenting with compact, diffuse and intracellular plaques as well as in post mortem human-AD brains." (PMID 28694463, 2017). "Amyloid plaque detection was more efficient in the strains having the largest plaques as observed in APPSL/PS1M146L, APP/PS1dE9 or APP23 with detection thresholds of 36 and 30 μm for in vivo and ex vivo images, respectively, which corresponds approximately to 1.2 times the voxel size." (PMID 28694463, 2017). "Although amyloid plaques were not present inIl33−/− mice, it is expected becausemurine APP lacks cleavage sties and hydrophobic residues for generating amyloidplaque." (PMID 28675392, 2017). "Conversely, the opposite strategy of inflicting neurotoxin-induced 5-HTergic deafferentation of the forebrain was shown to reduce levels of tau phosphorylation in the neocortex, but not amyloid pathology, in APP/PS1 mice." (PMID 28899417, 2017). "Here, we investigated the extent to which Gd-stained MRI allows detection of different types of amyloid lesions including compact, diffuse and intracellular amyloid deposits in five mouse models of amyloidosis (APPSL/PS1M146L, APP/PS1dE9, APP23, APPSwDI, 3xTg)." (PMID 28694463, 2017). "Together, these results indicate that co- injection of the AAV-APP and AAV-PS1 vectors into the hippocampus of normal mice leads to an overall pattern of amyloid processing close to that observed in the hippocampus of AD patients and contrasts to that of APP/PS1ΔE9 mice." (PMID 26759118, 2016). "We demonstrated, as expected, that in our hands female 5XFAD exhibited an increase in AD markers with age, including, an increase in APP and Bace1 expression, higher protein levels of BACE1 and sAPPβ, and higher number of amyloid plaques indicating the development of AD pathology in aged 5XFAD." (PMID 27013617, 2016). "Therefore, APP/PS1 mouse models are commonly used to assess the pharmacodynamics of potential pro-cognitive and amyloidosis-lowering compounds." (PMID 27421117, 2016). "Furthermore, in many models of Alzheimer’s disease, overexpression of mutant human APP is often combined with overexpression of mutant human presenilin 1 (PS1), which speeds up amyloidosis in double transgenic mice, compared to single APP transgenes." (PMID 26063233, 2015). "Platelets adhere to vascular amyloid-ß plaques in the brain of both, APP Dutch and APP23 mice supporting the hypothesis of active platelet recruitment to amyloid plaques." (PMID 24587388, 2014). "In another experiment T2 was measured in young APP/PS1 mice whose brains exhibited amyloidosis in the subiculum but had no detectable iron accumulation on histology." (PMID 25400539, 2014). "In addition to its role in the promotion of astrogliosis, IL-1 is known to induce marked expression of the amyloid precursor protein (APP) gene and α1-antichymotrypsin, both known components of amyloid plaques." (PMID 25005532, 2014). "It should be noted that BACE1 levels were significantly increased in the brains of D257A; APP/Ld and APP/Ld compared to D257A and wild-type mice, consistent with our previous work showing that BACE1 levels are elevated by amyloid pathology in human AD and APP transgenic mouse brains." (PMID 24885175, 2014). "While 57 was able to label amyloid deposits in APP/PS1 mice, its brain penetration was not as high as that of [11C]56c." (PMID 23766818, 2013). "We have evaluated FC in the brain of APP/PS1 mice, which is a mouse model for amyloidosis." (PMID 24358348, 2013). "In APP/PS1 mice, the first amyloid plaques appear in the cerebral cortex at 6 weeks of age." (PMID 22511962, 2012). "Similarly, amyloid plaques in APP mice contain mouse ACT and injecting Aβ1-11 into one side of the APP mouse brain to block ACT's binding site with endogenous Aβ rapidly reduced amyloid load compared to the other, vehicle-injected side of the brain." (PMID 22844635, 2012).
amyloid (continued). "A recent in vivo study reported that natural Aβ-antibodies (Nabs-Aβ) isolated from hIVIG reduced amyloid plaque burden in 3-month-old mice but not in 12-month-old APP transgenic mice." (PMID 22642812, 2012). "It was further reported that cell death in these APP/Tau mice preceded overt amyloid plaque formation and NFT formation and did not correlate with amyloid burden in any of the regions examined." (PMID 20871861, 2010). "We report that in addition to decreased mRNA expression, there was decreased overall Na+/K+ ATPase enzyme activity in the amyloid-containing hippocampi of the APP+PS1 mice (although not in the amyloid-free cerebellum)." (PMID 15689237, 2005). "In contrast, PSEN1 KI mice lacking the APP are not known to develop amyloid pathology." (PMID 41496612, 2026). "Total retinal thickness was comparable for the amyloidosis models (transgenic [tg] and non-transgenic [ntg] APP/PS1 = 209.3 μm and 210.7 μm, and tg and ntg 5xFAD = 212.1 μm and 211.2 μm), but, on average, approximately 17% thicker for the tg and ntg PS19 mice (256.4 μm and 236.8 μm)." (PMID 41235867, 2025). "The results showed that compared with the control group, the extracellular amyloid plaque deposition in the hippocampus of APP/PS1 mice was significantly increased, and there was no significant reduction in extracellular plaque deposition after DNLA administration." (PMID 40047153, 2025). "The key novelty of our study lies not in merely confirming sexual dimorphism in APP/PS1 mice, but in systematically identifying qualitatively distinct patterns of amyloid burden and their association with behavioral phenotypes under conditions of a restored neuroinflammatory response." (PMID 41300242, 2025). "Knocking out TREM1 in the brains of APP/PSEN1 mice has been shown to increase Aβ1–42 levels and total amyloid plaque burden, and selective overexpression or activation of TREM1 on microglia cells could improve Aβ neuropathology and rescue AD-related spatial cognitive impairments." (PMID 39626951, 2024). "Furthermore, supplementation with LA has been assessed in aged Tg2576 mice overexpressing APP, demonstrating improvement in learning and memory, despite not affecting the amyloid plaque deposition." (PMID 39290994, 2024). "Interestingly, no SBP differences were observed in the female APP/PS1 mice prior to or during the onset of amyloid pathology." (PMID 38862757, 2024). "Amyloid plaques are formed by extracellular aggregates Aβ, a 40–42 amino acid peptide derived from the amyloid precursor protein (APP), and the accumulation of lower-order aggregates of Aβ contributes to the death of neurons by interfering with synaptic function in critical areas of the brain." (PMID 38434588, 2024). "Contrary to expectations, these studies revealed that the early combined amyloid and tau pathologies resulted in enhanced synaptic strength as evidenced by increased LTP formation compared to age-matched rats displaying only the amyloid (APP+/−) or the tau (R955-hTau+/−) pathology." (PMID 39707506, 2024). "However, the 7-month-old male APP/PS1 mice showed a significant decrease in the time spent with the novel object compared to the controls, suggesting poor recognition in the male mice group during the onset of amyloid pathology." (PMID 38862757, 2024). "Moreover, global inflammasome inactivation through respectively full body deletion of caspases 1 and 11 in AppNL-G-F mice and Nlrp3 deletion in APP/PS1 mice also failed to modulate amyloid pathology and disease progression." (PMID 38352874, 2024). "Indeed, APP knock-in mice that more gradually develop amyloidosis without APP overexpression showed no oscillatory power changes at 3 moa and impaired gamma oscillations only at 6 moa." (PMID 37608393, 2023).
amyloid (continued). "Further analysis using fluorescence microscopy confirmed that the THK-565 signals corresponded to immunostained Aβin the brain sections of APP-KI mice, indicating that intravenously administered THK-565 could enter the brain and selectively bind to intracranial amyloid deposits." (PMID 37580462, 2023). "Overall, our results suggest that astrogliosis and microglial gene activation in APP/PS1 mice are significantly reduced by curative PEL24-199 treatment, and both processes might contribute to the rescue of the amyloid pathology and memory impairment in our PEL24-199-treated APP/PS1 mice." (PMID 36982363, 2023). "Our study results show that TBN could decrease the levels of APP, BACE1 and PS1, and increase the levels of NEP, indicated that TBN prevents the amyloid plaque formation and enhances amyloid degradation, which account for the reduction levels of Aβ production and deposition in 3×Tg-AD mouse model." (PMID 36950017, 2023). "Since AZD3293 significantly decreases plaque load and rescues sleep impairments in 5xFAD but not in APP KI mice, we asked whether these two AD mouse models would have functional differences in amyloid plaque clearance." (PMID 37536983, 2023). "Similarly, ChABC or treatment with an antibody recognizing the inhibitory 4-sulfated CSPGs found in PNNs, was able to restore normal NOR memory in an Alzheimer models (P301S tauopathy and the APP/PS1 amyloid model)." (PMID 36379919, 2022). "We studied brain endothelial permeability in female APPswe/PS1∆E9 (APP/PS1) mice which constitute a transgenic mouse model of amyloid-beta (Aβ) amyloidosis and found that permeability increases with aging in the areas showing the greatest amyloid plaque deposition." (PMID 36182964, 2022). "We found that self-renewal of microglia did not improve amyloid pathology, evidenced by the unaltered area fraction occupied by amyloid plaques, as well as the average size and number of plaques in either male 3xTg or APP/PS1 mice of both sexes." (PMID 35787714, 2022). "Since the App-KI mice showed Aβ accumulation without non-physiological APP overexpression, the motor dysfunction observed in this study may have been derived from Aβ amyloidosis." (PMID 35387663, 2022). "Notably, these synaptic changes occur in peri-adolescent animals in the absence of amyloid plaque pathology, despite an increase in Aβ and APP-metabolites produced by β-cleavage." (PMID 36438008, 2022). "However, SCFA treatment did not alter behavior, astrocyte activation, nor amyloid neuropathology in APP/PS1 mice maintained with a conventional microbiome." (PMID 35860296, 2022). "In the APP/PSEN1 mouse line, the hippocampal vascularization was reduced at the age of 4 months compared to wt, agreeing with earlier data, and suggesting that hypoperfusion may also contribute to amyloid pathology in familial AD." (PMID 35852609, 2022). "In addition, it can also restore APP/PS1 mouse hippocampus cell proliferation, differentiation reduction, and Aβ‐induced neural stem cells proliferation inhibition by decreasing the number of amyloid pathology via inhibition of PrP expression." (PMID 34672433, 2021). "Thus, the phenotype of Aβ amyloidosis in MITOL-deleted APP/PS1 mice, exhibiting an increase of Aβ oligomers but not of Aβ plaques, is unique and distinct from that of other gene transgenics/knockout mice with the enhancement of the self-assembly of Aβ." (PMID 33580194, 2021). "In light of these findings, WSB.APP/PS1 may be an ideal strain to dissect the relationship between amyloidosis, CAA, and vascular dysfunction in AD without the need to deplete brains of all microglia." (PMID 33567283, 2021). "It is unclear whether the appearance of rod-shaped microglia precede amyloidosis although no genotype-related change was observed in hippocampal tissue prepared from 3-month-old APP/PS1 mice compared with WT mice." (PMID 34112929, 2021).
amyloid (continued). "In double-transgenic amyloid precursor protein (APP)/presenilin 1 (PS1) murine models of AD, the role of DCs in amyloid plaque accumulation in the brain parenchyma is supported by evidence of increased formation of amyloid plaques following the systemic depletion of DCs." (PMID 32345316, 2020). "To determine whether amyloid pathology affected the membrane properties of OPCs, we performed whole‐cell patch‐clamp analysis of GFP+ OPCs in the hippocampus of brain slices collected from WT, MAPT, or APP transgenic mice carrying the Pdgfrα–H2BGFP transgene." (PMID 32557778, 2020). "Our observation that Gal-3 preferentially associates with Aβ monomers seems to explain why the distribution of Gal-3 does not completely overlap with amyloid plaque staining in APP/PS1 mice and AD patients, given that amyloid plaque largely consists of Aβ fibrils." (PMID 31127200, 2020). "Moreover, overexpression of NRBF2 reduced the amyloidosis of APP, and inhibition of NRBF2 could increase the amyloidosis of APP in AD cell models." (PMID 32998479, 2020). "Therefore, we investigated in the present study the AppNL-G-Fmodel, an App knock-in (App-KI) mouse model that develops amyloidosis in the absence of APP-overexpression." (PMID 31705038, 2019). "We have previously shown that sustained expression of IL-1β in the hippocampus of APP/PS1 mice decreases amyloid plaque burden independent of recruited CCR2+ myeloid cells, suggesting resident microglia as the main phagocytic effectors of IL-1β-induced plaque clearance." (PMID 31822279, 2019). "We next expressed the AAV-αAβ IgG in an amyloid plaque mouse model that expresses mutant amyloid precursor protein (APP mice) to assess the extent of brain transduction and determine whether the antibody is secreted into the extracellular space to bind amyloid plaques in vivo." (PMID 31887144, 2019). "Our study further confirms reports that APP and APP/PS1 transgenic mice do not exhibit the UPR and, moreover, questions whether amyloid pathology causes ER stress in AD." (PMID 30315100, 2018). "Moreover, changes in amyloid plaque load were not due to changes in the expression of proteins involved in amyloid precursor protein (APP) metabolism." (PMID 30322407, 2018). "Approximately 20% of neuronal processes exhibit aberrant calcium homeostasis leading to elevated levels of resting calcium, or calcium overload, in APP/PS1 mice aged 8–10 months with substantial amyloid pathology, and this is not related to the presenilin gene." (PMID 29378621, 2018). "One of these studies also described the effects of CD33-knockout in the APP/PS1 mouse model, in demonstrating that APP/PS1-CD33−/− mice displayed a significant decrease in amyloid plaque burden, without altering APP processing, compared to APP/PS1-CD33+/+ controls." (PMID 30249283, 2018). "For instance, the Tg2576 transgenic mouse drives expression of mutant APP using the same hamster prion protein gene promoter and there are no amyloid plaques in the thalamus even at 16 months of age, while several other brains regions have a significant plaque load." (PMID 28093491, 2017). "However, mice that model aspects of Down’s syndrome, including triplication of the mouse APP gene, do not develop AD-like amyloidosis." (PMID 26566997, 2015). "Ablation of the adaptive immune system, however, did not influence Aβ levels and glial cells in younger APP transgenic mice at a pre-plaque stage suggesting that the modulation of microglial responses to Aβ is specifically related to the presence of amyloid deposits." (PMID 26558367, 2015). "In addition to asking whether amyloid pathology affects the progression of tau pathology, we also compared the rTgTauEC x APP/PS1 and APP/PS1 mouse lines to assess the impact of human tau on amyloid deposition." (PMID 25853174, 2015).